REC8 (REC8 meiotic recombination protein)
Description:
Required during meiosis for separation of sister chromatids and homologous chromosomes. Proteolytic cleavage of REC8 on chromosome arms by separin during anaphase I allows for homologous chromosome separation in meiosis I and cleavage of REC8 on centromeres during anaphase II allows for sister chromatid separation in meiosis II (By similarity).
Synonyms: REC8L1; Rec8p; kleisin-alpha; HR21spB
Tractability: No criterion of Open Targets' tractability assessment is met for any kind of drug.
Gene: Protein-coding gene on chromosome 14 (24,171,853 to 24,180,923, forward strand). Ensembl gene ENSG00000100918.
Subcellular location: Nucleus; Chromosome; Chromosome, centromere
Subcellular location (Human Protein Atlas): Nucleoplasm
Pathways (Reactome):
Reproduction: Meiotic synapsis
Gene Ontology:
Molecular function: protein binding; chromatin binding
Biological process: double-strand break repair; establishment of meiotic sister chromatid cohesion; meiotic cell cycle; meiotic sister chromatid cohesion; reciprocal meiotic recombination; sister chromatid cohesion; spermatogenesis
Cellular component: chromosome; meiotic cohesin complex; nucleus; chromosome, centromeric region; cohesin complex; condensed chromosome; condensed chromosome, centromeric region; condensed nuclear chromosome; kinetochore; lateral element; male germ cell nucleus; synaptonemal complex
Genetic constraint (gnomAD): Loss-of-function variants: 43 observed, 81.31 expected, observed/expected ratio (o/e) 0.53, 90% interval 0.41 to 0.68. The upper end of that interval is the gene's LOEUF score, 0.68, which puts it in group 2 of 6, group 1 being the genes least tolerant of losing a copy. Missense variants: 578 observed, 742.85 expected, observed/expected ratio (o/e) 0.78, 90% interval 0.73 to 0.83. Synonymous variants: 268 observed, 288.97 expected, observed/expected ratio (o/e) 0.93, 90% interval 0.84 to 1.03.
Homologues: Orthologues: chimpanzee REC8 (99% identical), macaque REC8 (94% identical), pig REC8 (83% identical), rabbit REC8 (83% identical), dog REC8 (82% identical), guinea pig REC8 (82% identical), rat Rec8 (77% identical), mouse Rec8 (76% identical), tropical clawed frog rec8 (44% identical), zebrafish rec8b (33% identical), zebrafish rec8a (26% identical), Drosophila melanogaster vtd (19% identical). Paralogues in human: RAD21 (22% identical), RAD21L1 (19% identical).
Diseases named in the same sentence as REC8 in open-access papers:
REC8 is named in the same sentence as 33 diseases in open-access papers, as found by Europe PMC text mining. Sharing a sentence is not in itself a finding about the gene and the disease. The quoted sentences say what the papers report.
Infertility (7 papers, 2016 to 2025). "REC8- and SMC1β-null mutations are sterile because of meiotic failure, whereas Smc1βfl/fl;Gdf9-iCre female mice are fertile, in contrast to the infertility observed in our breeding trials." (PMID 34935904, 2021). "Deletion of meiosis-specific cohesin subunits in mice (Rec8−/−, Smc1b−/− and Rad21L−/−) showed defects in synapsis and infertility and premature reproductive senescence in Rad21L−/− females associated with a defect in primordial follicles." (PMID 26232174, 2016). "Mutation of Rec8 results in pairing of sister chromatids during prophase I rather than homologous chromosomes (leading to infertility of males and females), indicating that REC8 is responsible for limiting synapsis of homologs only." (PMID 34573322, 2021).
gastric cancer (6 papers, 2017 to 2022). A primary or metastatic malignant neoplasm involving the stomach. "The results suggest that methylation of the Rec8 gene promoter is an independent risk factor for reducing the survival in patients with gastric cancer." (PMID 33381453, 2020). "While addition of neutralizing antibody targeted VEGF into supernatant drastically reversed the effect of REC8 loss in gastric cancer cells on tube formation." (PMID 32958054, 2020). "The clinical analysis demonstrated that the loss of REC8 in gastric cancer with enrichment of MVD." (PMID 32958054, 2020). "Most importantly, the expression of REC8 level is negatively correlation with MVD in gastric cancer." (PMID 32958054, 2020). "Further investigation showed that supernatant from ablated of REC8 expression in gastric cancer cells drastically enhanced HUVEC tube formation by a co-cultured with HUVECs." (PMID 32958054, 2020). "In summary, in addition to the studies showed that the role of REC8 in tumor migration, invasion, cell proliferation, growth and apoptosis in gastric cancer." (PMID 32958054, 2020). "Inhibition of REC8 expression in gastric cancer cells contributed to tumor angiogenesis in the gastric cancer microenvironment." (PMID 32958054, 2020). "Our study is the first time to unravel the role and mechanism of REC8 in tumor angiogenesis by regulation of NF-κB-mediated VEGF expression in gastric cancer cells." (PMID 32958054, 2020). "Next, we investigated the effect of REC8 in gastric cancer cells on HUVECs migration using transwell model system." (PMID 32958054, 2020). "In contrast to other meiotic genes, reactivation of REC8 in mitotic cells was also shown to play a tumor suppressor role in certain cancer cell lines, such us gastric cancer cells where induced overexpression of REC8 inhibited cell proliferation, invasion and migration." (PMID 35251135, 2022). "REC8 have been proved to inhibit gastric cancer cell EMT by down-regulating EGR1 expression." (PMID 34889158, 2021). "Downregulation of REC8 was correlated with tumor angiogenesis in gastric cancer tissues." (PMID 32958054, 2020). "Depletion of REC8 expression in gastric cancer cells significantly increased tube formation of human umbilical vein endothelial cells (HUVECs), which is attributed to enhancement of vascular endothelial growth factor (VEGF) secretion caused by REC8 slicing." (PMID 32958054, 2020). "However, the role of REC8 in gastric cancer angiogenesis remains to be identified." (PMID 32958054, 2020). "This includes inference of a pseudomeiotic role for REC8 in endoploid cells induced after ionizing irradiation and the finding that REC8 might be a tumour suppressor required to inhibit the epithelial‐to‐mesenchymal transition in gastric cancers, possibly via a transcriptional regulation function." (PMID 31102330, 2019). "Silencing of REC8 expression in BGC823 and AGS-1 of gastric cancer cell promoted the phosphorylation of NF-κB p65 (Ser536), and no significance change of total NF-κB p65 was observed between shCTL and shREC8." (PMID 32958054, 2020). "It has been showed that REC8, a component of the meiotic cohesion complex, played a vital role in Epithelial-Mesenchymal Transition (EMT) in gastric cancer." (PMID 32958054, 2020).
lymphoma (6 papers, 2006 to 2022). A malignant (clonal) proliferation of B- lymphocytes or T- lymphocytes which involves the lymph nodes, bone marrow and/or extranodal sites. "REC8 protein participates in the segregation of homologs at the first meiotic division, and REC8 up-regulation determines the extent of arrested mitoses and polyploidy in lymphoma cell lines." (PMID 24403051, 2014). "Using the same antibodies, we then assessed the expression of REC8 in the lymphoma cells." (PMID 16401344, 2006). "Reduction divisions starting with diplochromosomes (not shown) and metaphase I-like segregation of REC8-cohesed centromeric dyads in a bipolar division presented here on HeLa cells has also been observed in IR-treated tetraploid lymphoma cells and by other researchers." (PMID 30691027, 2019).
melanoma (3 papers, 2013 to 2020). A malignant, usually aggressive tumor composed of atypical, neoplastic melanocytes. "Previous studies showed that REC8 was hypermethylated in melanoma and malignant gastrointestinal stromal tumor and, in the latter, hypermethylation of REC8 was associated with a poorer prognosis of the tumor." (PMID 26472282, 2015). "It has been reported that REC8 was hypermethylated in melanomas and malignant gastrointestinal stromal tumors, suggesting the low level of REC8 expression in tumor and a potential tumor suppressor." (PMID 32958054, 2020). "There was also a significant association between REC8 hypermethylation and AKT-pS473 phosphorylation and AKT- pT3083 phosphorylation in primary melanoma." (PMID 26472282, 2015). "REC8 expression has been noted in melanoma and we found it to be overexpressed in melanoma using western blot analysis and immunofluorescence." (PMID 23840955, 2013). "REC8 expression level showed again an inverse relationship with the PI3K activities in colon cancer and melanoma." (PMID 26472282, 2015). "Melanomas have also been shown to express meiosis specific proteins including SCP1 (homologous chromosome pairing), HORMAD1 (meiotic synapse regulation), SPO11 (double stranded DNA breaks), and REC8 (meiosis cohesion protein)." (PMID 23840955, 2013).
thyroid cancer (3 papers, 2015 to 2023). "We also observed an association between REC8 hypermethylation and thyroid cancer-related patient mortality." (PMID 26472282, 2015). "Methylation of REC8 was highly associated with the classical mutations that drive the PI3K pathway both in thyroid cancer cell lines and in thyroid cancers." (PMID 26472282, 2015). "REC8 hypermethylation was also strongly associated with poor clinicopathological outcomes of thyroid cancer patients, including advanced tumor and disease stages and patient mortality." (PMID 26472282, 2015). "REC8 hypermethylation was strongly associated with genetic alterations and activities of the PI3K pathway in thyroid cancer cell lines, thyroid cancer tumors, and some other human cancers." (PMID 36975440, 2023). "When all the thyroid cancers were analyzed collectively, REC8 methylation in cancer samples was also higher than that in the matched normal thyroid tissues." (PMID 26472282, 2015). "Our functional studies also directly demonstrated the inhibitory effects of REC8 expression on thyroid cancer cells." (PMID 26472282, 2015). "To functionally test a role of REC8 in thyroid tumorigenesis, we constructed REC8 expression vector and established stable transfectant thyroid cancer cell lines K1 and C643 with doxycycline-inducible expression of REC8." (PMID 26472282, 2015). "The study also demonstrates a prognostic value of REC8 hypermethylation for poor prognosis of thyroid cancer and potentially other cancers as well." (PMID 26472282, 2015). "No mutation was found on our sequencing of the exons of REC8 in thyroid cancer or on the analysis of the TCGA thyroid cancer database, suggesting that mutation of this gene is not a common event in thyroid cancer." (PMID 26472282, 2015). "It is worth noting that, among all types of thyroid cancers, hypermethylation of REC8 most prominently occurred in ATC, the most aggressive type of thyroid cancer, and was associated with advanced disease stages of thyroid cancer and thyroid cancer-related mortality." (PMID 26472282, 2015). "Demethylating the hypermethylated REC8 gene restored its expression in thyroid cancer cells in which the PI3K pathway was genetically over-activated and induced expression of REC8 protein inhibited the proliferation and colony formation of these cells." (PMID 26472282, 2015). "Treatment with the DNA-demethylating agent 5-Aza-2′-deoxycytidine induced promoter demethylation of REC8, which was otherwise normally hypermethylated by the genetically activated PI3K pathway, and restored its expression in 4 of the 5 thyroid cancer cell lines tested." (PMID 26472282, 2015). "Thus, an association between REC8 methylation and genetic alterations in the PI3K pathway, an inverse relationship between REC8 expression and genetic alterations in the PI3K pathway, and an inverse relationship between REC8 expression and REC8 methylation were observed in thyroid cancer cells." (PMID 26472282, 2015).
hepatocellular carcinoma (2 papers, 2023). A malignant tumor that arises from hepatocytes. "REC8, a cohesion that functions during meiosis, was previously linked to colorectal cancer and hepatocellular carcinoma by promoting invasiveness and metastasis." (PMID 37591832, 2023). "By targeting the PKA pathway, REC8 can promote tumor migration, invasion, and angiogenesis in hepatocellular carcinoma." (PMID 37143720, 2023).
anaplastic thyroid cancer (1 paper, 2020). "It is interesting to find that hypermethylation of the REC8 gene was uniquely more common in follicular thyroid cancer (FTC) and anaplastic thyroid cancer (ATC)." (PMID 32958054, 2020).
cervical cancer (1 paper, 2013). A primary or metastatic malignant neoplasm involving the cervix. "In addition, ectopic expression of some key meiotic genes was also reported in primary tumours, for example MOS in NSCLC, DMC1 in cervical cancer, SPO11, REC8, SGO1 and HORMAD1 in melanoma." (PMID 24025698, 2013).
cutaneous melanoma (1 paper, 2015). A primary melanoma arising from atypical melanocytes in the skin. "For example, we found a significant association between REC8 hypermethylation and genetic alterations in the PI3K pathway and a trend of inverse association between the REC8 mRNA expression and genetic alterations in the PI3K pathway in cutaneous melanoma." (PMID 26472282, 2015).
lentivirus infection (1 paper, 2020). Virus diseases caused by the Lentivirus genus. "To explore possible role of REC8 in the tumor angiogenesis, we established BGC823 and AGS-1 cells that stably expressed REC8 depletion by lentivirus infection and confirmed by real-time PCR and WB." (PMID 32958054, 2020).
leukemia (1 paper, 2022). A malignant (clonal) hematologic disorder, involving hematopoietic stem cells and characterized by the presence of primitive or atypical myeloid or lymphoid cells in the bone marrow and the blood. "Additionally, to test whether ESC differentiation changes the expression kinetics of REC8 and STAG3, we differentiated ESCs by withdrawing leukemia inhibitory factor from the culture medium." (PMID 35241136, 2022).
lymphoid tumours (1 paper, 2006).
neuroblastoma (1 paper, 2023). Neuroblastoma (NB) is the most common solid, extracranial childhood tumor. "REC8 knockdown significantly reduced neuroblastoma cell proliferation, migration, invasion, angiogenesis, induced cell cycle arrest, and enhanced apoptosis." (PMID 38105365, 2023).
Primary amenorrhea (1 paper, 2020). "This variant was also described in patients with primary amenorrhea, together with another mutation in the REC8 and FIGLA genes." (PMID 32155011, 2020).
sterility (1 paper, 2024). "The absence of REC8 cohesion leads to germ cell failure and female mouse sterility." (PMID 39659446, 2024).
thyroid tumor (1 paper, 2015). A benign or malignant neoplasm affecting the thyroid gland. "For example, 9/28 (32.14%) PI3K+ thyroid tumors versus 20/125 (16.00%) PI3K- tumors had a REC8 methylation level > X ̄+4SD (p = 0.049)." (PMID 26472282, 2015). "The results in our cell lines and thyroid tumors on the link between REC8 and the PI3K pathway were robust and fully replicated in the TCGA database." (PMID 26472282, 2015). "To explore further the relationship between REC8 methylation and the PI3K pathway, we examined the hotspot mutations of five classical genes in the PI3K pathway, including H-RAS, K-RAS, N-RAS, PIK3CA and PTEN in 157 thyroid tumor samples." (PMID 26472282, 2015). "We next examined the methylation status of REC8 and ADORA2B in human thyroid tumor tissues." (PMID 26472282, 2015).